SERPINA1 (serpin family A member 1)
Diseases named in the same sentence as SERPINA1 in open-access papers (continued):
Sharing a sentence is not in itself a finding about the gene and the disease.
liver disease (continued). "Clinically relevant mutations in the SERPINA1 gene, such as Z (Glu342Lys), results in an expression of misfolded AAT protein having high propensity to polymerize, accumulate in hepatocytes and thus to enhance a risk for hepatocyte damage and subsequent liver disease." (PMID 31832977, 2020). "CFLD and portal hypertension are substantially correlated with polymorphisms in the SERPINA1 gene, which codes for alpha-1 antitrypsin." (PMID 40804904, 2025). "The amount of precipitated Z-protein in the liver of SERPINA1 MZ heterozygotes increases with the severity of liver disease." (PMID 41004464, 2025). "In the gene SERPINA1, rare Mendelian mutations lead to alpha-1 antitrypsin (AAT) deficiency, with liver disease as part of the phenotype." (PMID 40593539, 2025). "Several mutations, including our high-PIP variant rs28929474C>T, in SERPINA1 can cause an autosomal co-dominant genetic disorder alpha-1 antitrypsin (AAT) deficiency, which can lead to lung or liver disease due to reduced alpha-1 antitrypsin levels." (PMID 39371129, 2024). "In a previous study, researchers found that the transcription factor C/EBP Homologous Protein (CHOP) cooperates with c-JUN to upregulate SERPINA1, thereby exacerbating the burden of proteotoxicity, which plays a significant role in liver disease progression." (PMID 38710698, 2024). "Many mutations in the SERPINA1 gene, responsible for encoding A1AT, are linked to lung disease, and some of these mutations lead to liver disease." (PMID 38397999, 2024). "Different mutations in the SERPINA1 gene result in alpha-1 antitrypsin (AAT) deficiency and in an increased risk for the development of liver diseases." (PMID 37569847, 2023). "Mutations in the Serpina1 gene cause AAT to form hepatoxic polymers, which can lead to reduced availability for the protein’s primary function and severe liver disease." (PMID 33539438, 2021). "On the other hand, the SERPINA1 Z-allele exerts its adverse biological effects by augmenting proteotoxicity in the endoplasmic reticulum, which may be particularly relevant in fibrogenic pathways as liver disease progresses to more advanced stages, while it is compensated for at earlier stages." (PMID 33804385, 2021). "Typical features of AAT deficiency-associated liver disease were analyzed in terms of AAT polymerization and secretion, and transcriptional induction of SERPINA1 gene transcripts in organoids subjected to external stimuli." (PMID 31832977, 2020). "The generation of authentic A1AT-D mouse-models has been hampered by the complexity of the mouse Serpina1-gene locus and a model with concurrent lung and liver-disease is still missing." (PMID 31097772, 2019). "Risk factors for the development of liver disease within CF patients have been described including an association with the SERPINA1 Z allele, a polymorphism in the alpha-1-antitrypsin gene." (PMID 30947265, 2019). "Mutations in the SERPINA1 gene can lead to AAT deficiency (AATD) which is associated with a substantially increased risk of lung and liver disease." (PMID 25425243, 2014). "Search for relevant articles were performed through Pub Med, HighWire, and Science Direct using the keywords “alpha-1-antitrypsin”, “liver diseases”, “hepatocellular carcinoma”, and “SERPINA1”." (PMID 23162602, 2012). "Search for relevant articles were performed through Pub Med, HighWire, and Science Direct using the keywords “alpha-1-antitrypsin”, “liver diseases”, “hepatocellular carcinoma”, “SERPINA1”." (PMID 23162602, 2012). "We show that the distribution of SERPINA1 c.-1973T >C in patients with liver disease from various aetiologies is similar compared to healthy controls." (PMID 20170533, 2010). "Apart from variations in the SERPINA1 gene, no potentially pathogenic variation was identified in genes known to be associated with liver disease." (PMID 41272759, 2025).
liver disease (continued). "Moreover, the coexistence of both the PNPLA3 G allele and SERPINA1 Pi*Z variant further amplified the risk of ACLD and CSPH, highlighting a synergistic effect of these genetic variants in the progression of liver disease and portal hypertension." (PMID 39997697, 2025). "The fibrogenic liver disease α1-antitrypsin (AAT) deficiency (AATD) is a genetic disorder caused by autosomal, codominant mutations in the SERPINA1 gene, resulting in misfolding and accumulation of AAT in hepatocytes." (PMID 40240610, 2025). "The late features of the liver disease in our cohort appeared to be associated only with the SERPINA1 genotype, while no significant impact of the PNPLA3 genotype was observed." (PMID 41004464, 2025). "Our study suggests that SERPINA1 defects may affect CVID clinical phenotype, since several genetic defects, including the common Z allele, were associated with liver disease." (PMID 38791420, 2024). "The Z allele of SERPINA1 gene, encoding AAT, is known as a risk factor for CF liver disease." (PMID 38655277, 2024). "The current AATD screening strategy may miss diagnoses whereas SERPINA1 sequencing may increase diagnostic yield for AATD, stratify risk for liver disease, and inform clinical management for individuals with AATD risk alleles and liver disease risk factors." (PMID 37651384, 2023). "Alpha-1 antitrypsin deficiency is caused by a mutation in the AAT (SERPINA1), leading to the misfolding and polymerization of the AAT protein that promotes fibrosis and cirrhosis upon accumulation in hepatocytes, leading to pulmonary and liver disease." (PMID 35326738, 2022). "While no specific CFTR mutations have been consistently linked to liver disease severity, environmental and genetic modifiers, such as the SERPINA1 Z allele, may play an important role in disease development." (PMID 41527672, 2026). "We also investigated other SERPINA1 variants and found that there was no increased prevalence of Z and S alleles in patients with liver disease of various aetiologies compared with healthy controls, even though we observed an enrichment of S allele heterozygosity in patients with DILI." (PMID 20170533, 2010). "For example, alpha-1-antitrypsin (SERPINA1) was selected because there was an increased level in SLE patients, but was found to diminish in other systemic autoimmune diseases and liver diseases." (PMID 35836976, 2022). "Furthermore, parameters evaluating the severity of liver disease, specifically the MELD score and patients’ age, differed significantly between subgroups of SERPINA1 MM homozygotes and MZ heterozygotes." (PMID 41004464, 2025). "Serum alpha-1-antitrypsin (AAT) levels, AAT phenotypes, and sequences of SERPINA1 gene were examined in a Chinese child with a moderate deficit of serum AAT, who had suffered several episodes of liver disease, as well as in his first-order relatives." (PMID 36186645, 2022). "Patient 2 harbors biallelic variants in SERPINA1, resulting in AATD, though these variants are unlikely to explain his phenotype, as PI typing IZ usually manifests in milder liver disease in childhood (Stoller, Hupertz, & Aboussouan, 2006)." (PMID 33960657, 2021). "The c.-1973T >C polymorphism located in the SERPINA1 promoter region is found more frequent in A1AT deficiency patients with liver disease compared to patients with pulmonary disease, but data are lacking regarding contribution to the development of liver diseases caused by other aetiologies." (PMID 20170533, 2010).
chronic obstructive pulmonary disease (116 papers, 2008 to 2026). A chronic and progressive lung disorder characterized by the loss of elasticity of the bronchial tree and the air sacs, destruction of the air sacs wall, thickening of the bronchial wall, and mucous accumulation in the bronchial tree. "Mutations in the SERPINA1 gene that codes for AAT are related to asthma and chronic obstructive pulmonary disease." (PMID 40781310, 2025). "In humans, A1AT deficiency is a disease caused by mutations in the SerpinA1-coding sequence and is known to cause chronic obstructive pulmonary disease (COPD) and liver cirrhosis." (PMID 39532838, 2024). "A family based study of predominantly smoking adults found methylation at two Cytosine-phosphate-Guanine sites (CpGs) in SERPINA1 gene to be associated with chronic obstructive pulmonary disease risk." (PMID 30134983, 2018). "The SERPINA1 variant was relatively pleiotropic, being associated with a range of traits including sex hormone–binding globulin levels, total testosterone, cholelithiasis, chronic obstructive pulmonary disease, CAD, and prostate cancer." (PMID 37096546, 2023). "A recent family based epigenome wide association study (EWAS) in predominantly smoking adults, reported a positive correlation between hypomethylation at two CpGs in SERPINA1 gene promoter from peripheral blood mononuclear cells (PBMCs) and chronic obstructive pulmonary disease risk." (PMID 33015055, 2020). "The aim of this study was to evaluate two missense single nucleotide polymorphisms (SNPs) (rs709932 and rs1303) in the SERPINA1 gene in Mexican mestizo patients with chronic obstructive pulmonary disease (COPD) related to tobacco smoking and biomass-burning exposure." (PMID 31892136, 2019). "We investigate here alternative 3′ polyadenylation in the SERPINA1 mRNA and its role in Chronic Obstructive Pulmonary Disease (COPD), a leading cause of death in the world." (PMID 34784346, 2021). "This year, 2013, is the fiftieth anniversary of the discovery of alpha one antitrypsin deficiency (AATD), a disease caused by mutation in SERPINA1, which predisposes to early onset lung disease, specifically chronic obstructive pulmonary disease (COPD)." (PMID 23990807, 2013). "Individuals with chronic obstructive pulmonary disease have an increase in long 3’UTR isoforms of SERPINA1 in lung tissue, potentially due to chronic inflammatory conditions." (PMID 40603521, 2025). "α-1 antitrypsin (AAT) is a serine proteinase inhibitor that plays an antiprotease protective role in the human body, and mutations in the gene SERPINA1 can lead to chronic obstructive pulmonary diseases by inducing AAT deficiency." (PMID 34112123, 2021). "The SERPINA1, SERPINA3, and SERPINE2 genes, which encode antiproteases, have been proposed to be susceptible genes for of chronic obstructive pulmonary disease (COPD) and related phenotypes." (PMID 21067581, 2010). "Point mutations in the SERPINA1 gene can lead to the misfolding, intracellular accumulation, and deficiency of circulating AAT protein, increasing the risk of developing chronic liver diseases or chronic obstructive pulmonary disease." (PMID 36142337, 2022). "The SERPINA1 gene is transcribed into multiple RNA isoforms that differ in their non-coding regions and influence production of the A1AT protein, which is associated with Chronic Obstructive Pulmonary Disease (COPD)." (PMID 34784346, 2021). "The absence of AAT or mutations in the SERPINA-1 gene promotes lung remodeling and fibrosis in diseases such as chronic obstructive pulmonary disease (COPD), and acute respiratory distress syndrome (ARDS) and increases the risk of allergic responses." (PMID 36671467, 2022). "Homozygosity for the SERPINA1 Z allele (rs28929474(T)) is the commonest cause of severe α1-antitrypsin deficiency (AATD) and is a well-established genetic risk factor for lung diseases such as chronic obstructive pulmonary disease (COPD)." (PMID 33981765, 2021).
chronic obstructive pulmonary disease (continued). "Isoelectric focusing may be used to genotype the SERPINA1 gene, including the PiMM genotype having normal AAT concentrations, the PiMZ genotype with mild AAT deficiency, and the PiZZ genotype with severe AAT deficiency (Global initiative for Chronic Obstructive Lung Disease, 2020)." (PMID 32461834, 2020).
lung disease (116 papers, 2007 to 2026). "The human orthologue of SERPINA1E is SERPINA1, which deficiency is known to be a molecular marker for lung diseases." (PMID 38909263, 2024). "For example, mutations in SERPINA1, encoding α1-antitrypsin, are associated with liver and lung diseases, including alpha-1 antitrypsin deficiency." (PMID 39063029, 2024). "Alpha-1 antitrypsin encoded by the SERPINA1 gene is the most abundant serine protease inhibitor (serpin) in human plasma and deficiency is known to cause lung disease." (PMID 36927357, 2023). "Apart from lung disorders, the mutational SERPINA1 gene increases the risk of inflammation in liver cells, leading to hepatocellular disorders." (PMID 36320441, 2022). "Alpha-1-antitrypsin deficiency (AATD) is a rare inherited condition caused by mutations of the SERPINA1 gene and is a genetic risk factor for liver and lung disease." (PMID 28915894, 2017). "Alpha-1-antitrypsin deficiency (AATD) is a rare inherited condition caused by mutations of the SERPINA1 gene that is associated with the development of a COPD like lung disease." (PMID 28915894, 2017). "Our study has significantly expanded the list of Null alleles known to occur within the SERPINA1 gene and underlined the importance of the correct diagnosis of this group of mutations, because of the particularly high risk of lung disease." (PMID 25425243, 2014). "Specifically, does carrying a single abnormal SERPINA1 allele increase risk of lung disease at the population level ?" (PMID 23990807, 2013). "Insertion of the Z-allele into the ferret SERPINA1 locus leads to both liver and lung disease." (PMID 35104244, 2022). "Clinically significant AATD-related lung disease occurs in approximately 1 in 2,500 Caucasian individuals who usually carry the PiZ or PiS variants of SERPINA1; importantly, both SNPs confer an increased risk of lung disease in carriers who smoke and in homozygous individuals who do not smoke." (PMID 23990807, 2013). "Alpha1 antitrypsin (AAT) deficiency, an autosomal codominant disease that is caused by mutation of the SERPINA1 gene, leads to liver and lung disease." (PMID 32825773, 2020). "Genes showing altered expression include a number of genes known to play important roles in lung disease such as α1-antitrypsin (SERPINA1), transforming growth factor β 1 (TGFβI), interleukin 1 receptor 1 (IL1R1) and IL6, IL8, IL1B, IL1A." (PMID 28335732, 2017). "Alpha-1 antitrypsin (A1AT) deficiency, caused by the Z allele (p.E342K) and S allele (p.E264V) in the SERPINA1 gene, can induce liver and pulmonary disease." (PMID 20170533, 2010). "With low levels of circulating SerpinA1, the lungs are not protected from neutrophil elastase, an enzyme that destroys alveoli and causes lung disease." (PMID 30009048, 2018). "Thus, the characterization at structural level of novel pathogenic SERPINA1 mutations coding for circulating AAT could provide novel insight into the mechanisms of AAT misfolding in liver and lung disease, with important implications for molecular diagnosis and therapeutic development." (PMID 36496391, 2022). "Studies have revealed that alpha 1 antitrypsin, a product of the SERPINA1 gene, can be used in the treatment of pulmonary disease." (PMID 36320441, 2022). "The deficient mutations in SERPINA1 caused the retention of A1AT in the liver followed by hepatocyte toxicity, and lack of A1AT in blood circulation leads to lung disorders." (PMID 40176953, 2025). "AAT lung disease is often treated with one of several serum protein replacement products; however, long-term studies of the effectiveness of SerpinA1 replacement therapy are not available, and it does not reduce liver damage in AAT deficiency." (PMID 30009048, 2018). "This indicates that both AAT levels and SERPINA1 genotypes should be revisited as potential biomarkers that warrant further study in the context of SCD, as well as considered for future therapeutic applications, especially the treatment of pulmonary disease." (PMID 29163550, 2017).
lung disease (continued). "A set of three most significantly upregulated proteins (HBB, CRP and SERPINA1) and four most significantly downregulated proteins (APOA2, AHSG, KNG1 and AMBP) were selected for validation in an independent cohort of IPF and other lung diseases using ELISA test." (PMID 28122020, 2017).